MICA (MHC class I polypeptide-related sequence A)
Diseases named in the same sentence as MICA in open-access papers (continued):
Sharing a sentence is not in itself a finding about the gene and the disease.
bladder tumor (3 papers, 2018 to 2025). "The NK-activating receptor natural killer group 2 member D (NKG2D) is important for tumor rejection by human NK cells after binding its tumor-associated ligand, major histocompatibility complex class I-related chain A (MICA), which is expressed on the human bladder tumor cell surface." (PMID 40566589, 2025). "For instance, the poly N-acetyllactosamine, the polymers of LacNAc mediated binding of galectin-3 to MHC class I-related chain A (MICA) has been demonstrated to contribute to the survival of bladder tumor cells and prevent the NK-mediated killing of C2GnT-expressing bladder tumor cells." (PMID 31355147, 2019).
chronic kidney disease (3 papers, 2017 to 2019). Impairment of the renal function secondary to chronic kidney damage persisting for three or more months. "This study expands our knowledge of the distribution of MICA polymorphisms and linkage disequilibrium with HLA-B alleles, helping to elucidate possible associations with different diseases in patients with chronic kidney disease." (PMID 28419176, 2017). "This information should help to determine the mechanisms of susceptibility to different diseases in patients with chronic kidney disease, and to elucidate the mechanisms involved in allograft rejection associated with MICA polymorphisms in a Brazilian population." (PMID 28419176, 2017). "Subsequently, Lemy and colleagues studied for the presence of MICA antibody in sera from 494 healthy controls and 597 patients with chronic kidney disease (CKD) stage V and reported threefold higher prevalence of MICA antibodies in patients with CKD when compared with controls." (PMID 28293239, 2017). "Here, we evaluated the impact of MICA, NKG2D and HLA-G genotypes as well as the sMICA and sHLA-G levels, comparing patients with chronic kidney disease with controls and patients who had undergone a kidney transplant and developed rejection with those who did not." (PMID 30794652, 2019).
colon adenocarcinoma (3 papers, 2008 to 2023). "Patients showed higher levels of MICA expression in cholangiocarcinoma (CHOL), colon adenocarcinoma (COAD), esophageal carcinoma (ESCA), head and neck squamous cell carcinoma (HNSC), kidney renal clear cell carcinoma (KIRC), liver hepatocellular carcinoma (LIHC), stomach adenocarcinoma (STAD)." (PMID 37784183, 2023).
diabetes (3 papers, 2014 to 2020). "They observed soluble MICA in sera and upregulated MICA expression in atherosclerotic plaques of patients with type 2 diabetes mellitus." (PMID 25352848, 2014).
Ewing sarcoma (3 papers, 2012 to 2023). A small round cell tumor that lacks morphologic, immunohistochemical, and electron microscopic evidence of neuroectodermal differentiation. "Independently, entinostat augmented the expression of ULBP1, HLA, and MICA/B on both rhabdomyosarcoma and Ewing sarcoma cell lines." (PMID 32499867, 2020). "Therefore, and based on the in situ expression of MICA in Ewing sarcoma tumours, soluble MICA expression levels were measured in plasma samples from Ewing sarcoma patients." (PMID 22587892, 2012).
graft versus host disease (3 papers, 2014 to 2025). An immune system disorder that occurs after allogeneic hematopoietic stem cell transplant and is a reaction of donor immune cells against host tissues. "Soluble MICA (sMICA) concentrations after allogeneic hematopoietic stem cell transplantation (HSCT) were associated with worse outcomes and graft-versus-host disease (GVHD)." (PMID 40538407, 2025). "In addition, antibodies of MHC class I chain related antigens A (MICA) had been educated much interest in HSCT, which showed that the presence of anti-MICA antibody before transplantation could confer protection against graft-versus-host disease (GVHD)." (PMID 38378602, 2024).
lymph node metastasis (3 papers, 2011 to 2024). "Clinicopathologic analyses did not reveal that MICA/B expression was associated with patient gender, tumor stage, and lymph node metastasis, and differentiation." (PMID 21605422, 2011). "In multivariate analysis, FIGO stage, lymph node metastasis, high ULBP1 expression and high combined MICA/B and ULBP1 expression were independent predictors of good prognosis." (PMID 25510288, 2014).
pancreatic ductal adenocarcinoma (3 papers, 2011 to 2023). An infiltrating adenocarcinoma that arises from the epithelial cells of the pancreas. "ADAM10 upregulation prompted membrane major histocompatibility complex class I chain-related gene A (MICA) shedding from pancreatic ductal adenocarcinoma cell surfaces and conversion to soluble MICA to degrade NKG2D on NK cells." (PMID 36797245, 2023). "A very recent study showed that MICA/B expression was detected in 92 of 103 pancreatic ductal adenocarcinomas from a cohort of Chinese patients." (PMID 21605422, 2011). "Vδ1 T cells express one of various Vγ chains (Vγ 2, 3, 4, 5, or 8) and recognize microbial- and self-lipids bound to CD1d molecules or stress-induced MHC class-I related chain A (MICA), that are frequently expressed on tumor cells including pancreatic ductal adenocarcinomas cells (PDAC)." (PMID 31555275, 2019). "MICA/B expression was positive in 17 of 25 (68%) pancreatic ductal adenocarcinomas but not in normal pancreatic ductal epithelial cells." (PMID 21605422, 2011).
prostate tumor (3 papers, 2014 to 2025). "The prostate tumor cell lines expressed high levels of MICA/B and ULBP1/2/3, which are ligands for the activating receptor NKG2D, and these observations were confirmed through detection with NKG2D-Fc recombinant protein." (PMID 25961317, 2015). "Variable NKG2D-ligand expression was observed in different PC lines, but all prostate tumor cells examined were positive for ULBP-2 and MICA/B ligands." (PMID 25268476, 2014).
psoriatic arthritis (3 papers, 2011 to 2024). Joint inflammation associated with psoriasis. "Independent of HLA-B and HLA-C, the MICA-129Met allele, especially Met/Met homozygosity, had a strong correlation with the two types of cutaneous psoriasis (PsC) and psoriatic arthritis (PsA)." (PMID 38474281, 2024).
renal cell carcinoma (3 papers, 2021 to 2023). "For instance, the overexpression of MMP-2 on the surface of renal cell carcinoma and membrane-type MMP-14 activity directly led to MICA shedding." (PMID 34502191, 2021).
sarcoma (3 papers, 2020 to 2025). A usually aggressive malignant neoplasm of the soft tissue or bone. "The mRNA expression of MICA/B and ULBPs was upregulated by the combination in all seven sarcoma cell lines, compared to untreated controls and single agents." (PMID 40986050, 2025). "On the contrary, most of the early stage and well-differentiated sarcomas were shown to express MICA on the cancer cell surface, indicating that MICA expression is lost along the disease progression." (PMID 33322371, 2020). "A narrow-spectrum HDACi entinostat has been shown to increase both NKG2D expression on NK cells and MICA/B in multiple tumor target cells, including sarcomas, augmenting NK cell cytotoxicity in vitro and in vivo and consequently suppressing sarcoma lung metastases in mice." (PMID 33322371, 2020). "Therefore, MICA shedding might be an early event in sarcoma immunoevasion, contributing to the disease progression." (PMID 33322371, 2020). "Different combinations of NK cell-activating ligands such as MICA/B ULBP1/2/3/5, CD155, and CD112 are known to be expressed on both primary sarcoma samples and cell lines, allowing for NK cell cytotoxicity." (PMID 33322371, 2020). "Several tumor histotypes, including sarcomas, express NK/CIK activating ligands, among which the NKG2D ligands (NKG2DLs), such as the stress-inducible ligands MHC class I chain-related protein A and B (MICA/B) and the UL16 binding proteins (ULBP2/3/5/6)." (PMID 40986050, 2025). "Our results show that over-expression of the activating receptor DNAM-1 or NKG2D on NK-92 cells induces efficient anti-sarcoma responses in vitro by amplifying the interaction with prevalent ligands CD112 and CD155 or MICA/B and ULBP1-5, respectively, on sarcoma and other tumor cells." (PMID 32082316, 2020).
Allergy (2 papers, 2013 to 2014). An allergy is an immune response or reaction to substances that are usually not harmful. "Finally, it is also interesting to note that 1 locus (rs9266772) near HLA-C and MICA has been recently identified as one of the loci of allergy-specific susceptibility." (PMID 24324648, 2013).
Arthritis (2 papers, 2013 to 2025). Inflammation of a joint. "Additionally, Type I peripheral arthritis has been linked to HLA-B27 and HLA-B35, while Type II arthritis is more strongly associated with HLA-B44 and the MICA*008 variant of the Major Histocompatibility Complex Class I-related protein A (MICA)." (PMID 40095525, 2025). "MICA-A9 (corresponding to MICA*002) polymorphism has been further associated with arthritis susceptibility but not with psoriasis." (PMID 23690822, 2013).
atherosclerosis (2 papers, 2017 to 2020). A disease characterized by the build-up of fatty material and calcium deposition in the arterial wall resulting in partial or complete occlusion of the arterial lumen. "In addition, all types of MICA/B+ MPs were positively correlated with hs-CRP, which is a biological marker of inflammatory diseases including atherosclerosis." (PMID 33003303, 2020).
bladder cancer (2 papers, 2023 to 2024). "One study reported that Galectin-3 can bind to MICA, which is a ligand to the activating NK cell receptor NKG2D, and that this Galectin-3-MICA complex caused disturbed interaction with NKG2D and thereby reduced NK cell killing of bladder cancer cells." (PMID 39759523, 2024).
Cirrhosis (2 papers, 2019 to 2020). A chronic disorder of the liver in which liver tissue becomes scarred and is partially replaced by regenerative nodules and fibrotic tissue resulting in loss of liver function. "A recent smaller study conducted in Europeans suggested an association between DEPDC5 rs1012068 but not MICA rs2596542 and risk of cirrhosis in chronic HCV infection." (PMID 30723271, 2019). "Interestingly, in that study, MICA rs2596542 showed a tendency for significance with cirrhosis (p = 0.07) in the discovery cohort (n = 477) but was not investigated in the validation cohort." (PMID 30723271, 2019).
cutaneous malignant melanoma (2 papers, 2004 to 2015). "Nevertheless, studies with larger series are required to find out whether MICA*002 allele may result in protection from cutaneous melanoma." (PMID 25838620, 2015). "In conclusion, our data demonstrate a lack of association between MICA polymorphism in the extracellular domains and cutaneous malignant melanoma, at least in our population." (PMID 25838620, 2015). "All these studies, as well as ours, have failed to establish an association between MICA gene polymorphism and an increased risk of developing cutaneous malignant melanoma." (PMID 25838620, 2015).
depression (2 papers, 2021 to 2024). "The major histocompatibility complex class I chain-related gene A MICA is a highly polymorphic gene that encodes protein variants functioning in immune activation and surveillance; our results therefore indicate that there may be a link between MICA and depression." (PMID 34349785, 2021). "Overall, MICA could be an interesting new shared target for future research on the shared pathogenesis, e.g. in the synaptic plasticity in hippocampus, in depression and AD." (PMID 38862462, 2024). "Besides, MICA seems to play a role in myelination and white-matter involvement is well documented for both depression and AD." (PMID 38862462, 2024). "The overlapping eQTL genes between AD and depression (SRA1, MICA, PCDHA8, PCDHA10, PCDHA7, and PCDHA13), were not yet associated with these disorders through proximity analysis nor have an established role in these diseases as of yet." (PMID 38862462, 2024).
fibrosarcoma (2 papers, 2018 to 2021). A malignant mesenchymal fibroblastic neoplasm affecting the soft tissue and bone. "Our results are based on an array ofin vivo models including MCA-induced fibrosarcoma in an immunocompetent ad hoc MICA-transgenic mouse model, and PDX." (PMID 35967081, 2021). "Importantly, MCA-induced fibrosarcomas displayed cell-surface MICA expression." (PMID 35967081, 2021).
gastric adenocarcinoma (2 papers, 2004 to 2024). "In this study, we have shown that the MICA allele A9 was significantly correlated with gastric adenocarcinoma and less schirrous change in gastric cancer tissue." (PMID 15150599, 2004). "In gastric adenocarcinoma, the elevated MICA/B levels in the lamina propria were likely a consequence of immune evasion by the cancer itself, since H. pylori is usually lost from the stomach with the development of advanced disease, and undetectable by the time of clinical cancer diagnosis." (PMID 38318189, 2024).
hearing loss (2 papers, 2019 to 2022). "The allelic variant may associate with the progression of hearing loss in patients with MD, such as major histocompatibility complex class I chain-related A (MICA) and Toll Like Receptor 10 (TLR10)." (PMID 35683514, 2022).
HIV-1 infection (2 papers, 2013 to 2018). The type species of lentivirus and the etiologic agent of acquired immunodeficiency syndrome (AIDS). "Furthermore, elevated levels of soluble MICA have been shown to impair NK cell function in chronic HIV-1 infection." (PMID 23372753, 2013).
Hodgkins lymphoma (2 papers, 2015 to 2021). A heterogeneous group of malignant lymphoid neoplasms of B-cell origin characterized histologically by the presence of Hodgkin and Reed-Sternberg (HRS) cells in the vast majority of cases. "NK cell function impairment was also explored in Hodgkin lymphoma (HL), where it correlated with elevated serum levels of soluble ligands for NK cell receptors NKp30 (BAG6/BAT3) and NKG2D (MICA), which are known to constrict NK cell function." (PMID 34203935, 2021).
Hyperglycemia (2 papers, 2019 to 2021). An increased concentration of glucose in the blood. "Hyperglycemia increased Bmi1 and GATA2 level, and decrease MICA/B and p-AMPK in vivo, as determined with IHC assessment." (PMID 31088566, 2019).
liver cirrhosis (2 papers, 2018 to 2019). "Specifically, MICA 251 Gln, MICA 175 Gly, MICA 129 Met, or a promoter region variant MICA rs259654A are significantly more prevalent in HBV-infected individuals that progress to HCC than in HBV-infected individuals who developed liver cirrhosis, but not HCC." (PMID 30150983, 2018).
lupus nephritis (2 papers, 2017). Glomerulonephritis in the context of systemic lupus erythematosus. "However, enhanced cell segregation to inflammatory sites may also contribute to the reduced ULBP1- and/or MICA/B-positivity cells among jSLE monocytes, as sequestration of myeloid cells to renal tissue has been described for patients with active lupus nephritis." (PMID 28944101, 2017).
medulloblastoma (2 papers, 2013 to 2023). A malignant, invasive embryonal neoplasm arising from the cerebellum. "Although NK cells have potent cytotoxic effects on medulloblastoma cells through the NKG2D/MICA-ULBP-2 interaction, high expression of HLA-I can protect medulloblastoma cells from the cytotoxicity of NK cells." (PMID 37705736, 2023). "MICA/ULBP-2 positive cells and intensity of cytoplasmic staining by immunohistochemistry on medulloblastoma tumors." (PMID 23626949, 2013).
megacolon (2 papers, 2012 to 2019). "HLA-non classical class I, MICA*011, which was closely linked to HLA-B*14 and DRB1*01 might also be functional as MICA is known to stimulate gamma-delta T-cells in the gut mucosa; a phenomenon that could relate to megacolon." (PMID 22448298, 2012). "The association of MICA*011 and HLA-B*14 and DRB1*01 could relate to megacolon." (PMID 31126327, 2019).
monoclonal gammopathy (2 papers, 2017 to 2020). A condition characterized by the abnormal presence of monoclonal immunoglobulins in the blood or urine. "In the context of monoclonal gammopathy, expression of MICA is known to decrease upon transition from pre-cancerous monoclonal gammopathy of undetermined significance (MGUS) to MM." (PMID 29163516, 2017).
pericarditis (2 papers, 2016 to 2020). An inflammatory process affecting the pericardium. "Our findings imply on a potential role for MICA in pericarditis, as it is associated with recurrence." (PMID 26909604, 2016). "In normal donors, MICA positively correlates with age, a correlation that is lost in pericarditis patients." (PMID 26909604, 2016). "Here we report for the first time on CEACAM1 as a potentially novel biomarker for pericarditis, as well as on MICA as an innovative prognostic marker in these patients." (PMID 26909604, 2016). "This argues against a significant diagnostic role for MICA and MICB in pericarditis." (PMID 26909604, 2016). "Collectively, these prompted the investigation of serum CEACAM1, MICA and MICB in pericarditis patients." (PMID 26909604, 2016). "Here we investigate the involvement of serum CEACAM1, MICA and MICB, proteins that can be induced in damaged or inflamed tissues, in pericarditis patients." (PMID 26909604, 2016). "As some of these conditions may play a role in pericarditis, upregulation of CEACAM1, MICA or MICB could be anticipated in situ." (PMID 26909604, 2016). "Serum MICA and MICB levels were elevated in some of the pericarditis patients, but without reaching statistical significance or efficient ROC curves." (PMID 26909604, 2016).
sarcoidosis (2 papers, 2019 to 2023). Sarcoidosis is a multisystemic disorder of unknown cause characterized by the formation of immune granulomas in involved organs. "The proliferation reactions of PBL from patients with BD after stimulation by candidate peptides (HSP65PD and B51PD) and control peptides (MICA-TM and Topo1PD) were compared to those of PBL from disease controls (sarcoidosis, VKH, SSc) and HC." (PMID 31513650, 2019).
small cell lung carcinoma (2 papers, 2024 to 2025). Small cell lung cancer (SCLC) is a highly aggressive malignant neoplasm, accounting for 10-15% of lung cancer cases, characterized byrapid growth, and early metastasis. "Conversely, several researchers have observed that increased MICA expression in HCC and small-cell lung cancer (SCLC) is associated with poor prognosis." (PMID 40723248, 2025). "Conversely, several studies have reported that elevated MICA expression in HCC and small cell lung cancer (SCLC) is associated with an unfavorable prognosis." (PMID 38254761, 2024).
triple-negative breast carcinoma (2 papers, 2021 to 2025). An invasive breast carcinoma which is negative for expression of estrogen receptor (ER), progesterone receptor (PR), and human epidermal growth factor receptor 2 (HER2). "This interaction alters the expression of miR-34a and miR-17–5p and modulates MICA//MICB (MHC class I-related chain A and B), PDL1 (programmed death ligand-1), and B7-H4 (member of B7 family) expression on triple-negative breast cancer cells." (PMID 40863726, 2025).
acute hepatitis A (1 paper, 2018). "Recently, it has been reported that in acute hepatitis A patients, NKG2DhighCD8+ T cells induced by IL15 promote damage of liver tissue expressing NKG2D ligands such as MICA and MICB." (PMID 30333822, 2018).
acute lymphoblastic leukemia (1 paper, 2013). Leukemia with an acute onset, characterized by the presence of lymphoblasts in the bone marrow and the peripheral blood. "In acute lymphoblastic leukemia (ALL), expression of the NKG2D activating receptor ligands MICA/B was only observed in NK sensitive T-ALL cell line, while NK-resistant B-ALLs did not express detectable amounts of MICA/B." (PMID 24391641, 2013).
amyloidosis (1 paper, 2019). A disorder characterized by the localized or diffuse accumulation of amyloid protein in various anatomic sites. "For example, alleles in other genes including MHC class-I polypeptide-related sequence A (MICA) and serum amyloid A-1 protein (SAA1) are associated with a severe FMF phenotype and increased susceptibility to amyloidosis." (PMID 31088470, 2019).